FUS (FUS RNA binding protein)
Diseases named in the same sentence as FUS in open-access papers (continued):
Sharing a sentence is not in itself a finding about the gene and the disease.
proteinopathies (continued). "Furthermore, the fact that geneticmodifiers uncovered in screens for TDP-43 and FUS proteotoxicty are surprisinglydistinct argues further that there are likely different underlying pathogenicmechanisms for FUS and TDP-43 proteinopathies." (PMID 21541367, 2011). "In addition to CBD, other underlying pathologies such as progressive supranuclear palsy, Alzheimer’s disease (AD), TDP-43 proteinopathy, fused in sarcoma (FUS) proteinopathy, prion disease, cerebrovascular pathology, and in rare instances even synucleinopathies have been reported." (PMID 41018194, 2025). "One such endogenous ‘barrier’ relevant to FUS proteinopathy may be the sequence differences between mouse and human FUS (which differ in 26 out of 526 amino acids), fifteen of which are located in the G-rich, prion-like domain believed to be a major factor in driving aggregation." (PMID 38862967, 2024). "It has been hypothesized that key proteins associated with ALS proteinopathies including TDP-43, FUS, VCP, and hnRNPA1 are examples of ‘essential’ proteins capable of starting a snowballing pathophysiological cascade due to their widespread roles or large numbers of downstream binding partners." (PMID 35002606, 2021). "Importantly, by introducing multiple mutations in the RRM RNA-binding domain of R495X FUS, to reduce its RNA-binding ability, they partially abrogated R495X-induced effects on mRNA translation, mitochondrial size, and neurotoxicity, uncovering a novel RNA-mediated pathway of FUS proteinopathy." (PMID 32582692, 2020). "Moreover, although an increasing number of studies have clearly revealed the important role of lncRNAs in many neurological diseases, it has not yet been established whether they also play a role in the pathogenesis of FUS-proteinopathies." (PMID 29142303, 2017). "Under these conditions, the mis-regulation of some lncRNAs may not only be a consequence of FUS aggregate formation, as previously proposed, it may also be an instigating event of FUS-proteinopathies such as alterations in FUS expression and specific targeting/packaging into harmless deposits." (PMID 29142303, 2017). "Although our data do not rule out the possibility that loss of function caused by sequestration of the wild-type FUS protein into inclusion bodies may also contribute to pathogenesis of FUS-proteinopathies, as previously proposed, the present study supports the gain-of-function toxicity mechanism." (PMID 26335776, 2015). "Our data show that down-regulating the expression of HSP60A, HSP60B or HSP60C led to a partial rescue of the neurodegenerative phenotypes in FUS transgenic flies to various extent, suggesting that these three genes may share common features in FUS proteinopathies." (PMID 26335776, 2015). "Moreover, HSP60 signaling pathway may be critical for FUS-induced neurotoxicity, and reducing HSP60 expression or suppressing HSP60 activity may provide therapeutic benefit for FUS-proteinopathies patients with increased HSP60 expression." (PMID 26335776, 2015). "Our data also uncover the previously unknown regulation of FUS subcellular distribution by chaperon proteins such as HSP60, suggesting a new direction for treating FUS proteinopathies by modulating mitochondrial localization of FUS and protecting against FUS-induced mitochondrial damage." (PMID 26335776, 2015). "FTLD is a proteinopathy, and the main pathological proteins identified so far are tau, TAR DNA-binding protein 43 (TDP-43), and fused in sarcoma (FUS)." (PMID 37371103, 2023). "Although the coexistence of AGD and FTLD-TDP or LATE-NC is common, the combination of three proteinopathies (i.e., tau, TDP-43, and FUS) is rare." (PMID 37415197, 2023). "Proteinopathies of β-amyloid, tau, α-synuclein, TAR DNA-binding protein 43 (TDP-43), fused in sarcoma (FUS), and prion protein account for the vast majority of human neurodegenerative diseases." (PMID 35813946, 2022).
proteinopathies (continued). "Our work provides strong evidence that mitochondrial damage contributes to FUS-proteinopathies and represents a common molecular pathology shared by ALS-FUS and FTLD-FUS." (PMID 26335776, 2015). "Unique proteinopathies are also a feature of SOD1- and FUS-related familial ALS." (PMID 40563773, 2025). "Here, we review the neuropathological and genetic evidence of oligodendrocyte impairment in TDP-43/FUS-proteinopathies, summarize current insights into the roles of TDP-43 and FUS in oligodendrocytes, and discuss the potential impact of altered oligodendroglial functions in ALS/FTLD pathogenesis." (PMID 34539339, 2021). "Moreover, the cytoplasmic mislocalization, aggregation, and co-aggregation of TDP-43, FUS, and SOD1 can be identified as proteinopathies akin to other neurodegenerative diseases (NDs), eliciting strong ties to disrupted RNA splicing, transport, and stability." (PMID 32422969, 2020). "This is mostly due to the presence of aberrant protein states (proteinopathy) of two essential RNA/DNA binding proteins TDP-43 and FUS (Fused in sarcoma) in affected neurons, including cytosolic translocation, truncation, phosphorylation, ubiquitination, and aggregates formation." (PMID 29109677, 2017). "ALS-linked mutations in the RBP fused in sacroma (FUS) lead to its mislocalization from the nucleus to the cytoplasm and aggregation, but they do not cause TDP-43 proteinopathy." (PMID 25652699, 2015). "After initial testing to exclude cases with non-specific protein degradation, three FUS-proteinopathies brains together with six control samples were identified suitable for biochemical studies and electron microscopy." (PMID 26335776, 2015). "Similarly, fibril-induced FUS aggregates co-localized with p62 and ubiquitin (as described in human FUS proteinopathies), but did not contain detectable levels of TDP-43." (PMID 38862967, 2024). "To date, four major proteinopathies have been identified in FTD patients: Tau, TAR DNA-binding protein 43 (TDP-43), fused in sarcoma (FUS), and ubiquitin positive inclusions, the latter comprising unknown aggregated proteins; with the first two accounting for the vast majority of cases." (PMID 35281504, 2022). "However, the finding that promoting glucose metabolism in FUS and TDP-43 proteinopathies ameliorates disease phenotypes indicates that glucose metabolism could be a driver of FTD pathophysiology and therefore could become a promising therapeutic target." (PMID 35281504, 2022). "The present results also contribute to our understanding of the pathomechanism of FUS-proteinopathies and indicate that a lncRNA-dependent mechanism may manage aggregation-prone hnRNPs such as FUS in non-toxic inclusions." (PMID 29142303, 2017). "Therefore, FUS and TDP 43-proteinopathies possibly cause gross RNA dysregulation rather than specific mRNA disruptions in ALS/FTD development." (PMID 29203801, 2017). "This is the first report of direct mitochondrial targeting by a nuclear protein associated with neurodegeneration, suggesting that mitochondrial impairment may represent a critical event in different forms of FUS-proteinopathies and a common pathological feature for both ALS-FUS and FTLD-FUS." (PMID 26335776, 2015). "Taken together with FUS and C9ORF72, these ALS-linked genes indicate that RNA processing deficits can be a cause of ALS in the presence or absence of TDP-43 proteinopathy, and that rescue of RNA processing defects could be beneficial to patients." (PMID 25652699, 2015). "Furthermore, it appeared extremely hard to achieve aggregation and respective proteinopathy in models with expression of full-length FUS or FUS lacking functional NLS, indicating that an additional event(s) is probably required to trigger aggregation of these proteins." (PMID 23867462, 2013).
myxoid liposarcoma (46 papers, 2010 to 2025). A liposarcoma characterized by the presence of round non-lipogenic primitive mesenchymal cells and small signet ring lipoblasts within a myxoid stoma with a branching vascular pattern. "Originally described as the result of translocations in myxoid liposarcoma, FUS encodes a TET protein that exerts roles in transcription and splicing and functions in several aspects of growth control and DNA repair." (PMID 21151896, 2010). "Instead, FUS::DDIT3-bound SWI/SNF complexes in myxoid liposarcoma cells are enriched in PBAF and GBAF components as well as most interaction partners." (PMID 40988026, 2025). "The FUS/EWSR1-DDIT3 fusion characteristic of myxoid liposarcoma can be distinguished from LLT using DDIT3 immunohistochemistry, in which nuclear anti-DDIT3 immunoreactivity is a highly sensitive and specific marker of myxoid/round cell liposarcoma." (PMID 41230282, 2025). "Myxoid liposarcoma harbors FUS/EWSR1-DDIT3 fusions, and nuclear DNA damage-inducible transcript 3 (DDIT3) immunoreactivity is a highly sensitive and specific marker." (PMID 41230282, 2025). "Conversely, myxoid liposarcomas with DDIT3 translocations (FUS::DDIT3 fusion) generally respond better to radiotherapy, highlighting the variability in treatment responses based on specific genetic profiles." (PMID 39229483, 2024). "Genetically, myxoid liposarcoma is associated in 95% of cases with a t translocation that results in a FUS-DDIT3 (formerly FUS-CHOP) juxtaposition." (PMID 39315063, 2024). "The YAP1:TFE3-fused gene and WWTR1(TAZ)-CAMTA1 gene fusions are characteristic of haemangioendothelioma, whereas the presence of FUS:DDIT3 or EWSR1:DDIT3 genes is pathognomonic in myxoid liposarcoma (MLPS), a malignant tumour, recapitulating lipogenesis." (PMID 37681936, 2023). "To study the cell of origin of myxoid liposarcoma, we generated novel genetically engineered mice with a Cre-activatable FUS-CHOP translocation transcript." (PMID 31427882, 2019). "Among the EWSR1-negative samples, 29 samples were positive for a FUS rearrangement either by FISH or RT–PCR: 18 cases were diagnosed as myxoid liposarcoma, 9 cases as LGFMS and 2 cases as SEF." (PMID 28141799, 2017). "Myxoid liposarcoma, characterized by the expression of the oncogenic transcript FUS-CHOP, was extremely sensitive to trabectedin." (PMID 28166781, 2017). "Myxoid liposarcoma is heterogeneous tumor and, as such, targeting FUS-CHOP or downstream targets of FUS-CHOP is only partially efficacious." (PMID 27822137, 2016). "The knockdown of FUS-CHOP in myxoid liposarcoma cells inhibited cell growth, induced cell cycle arrest, and reduced expression of VEGFR1 and the angiogenic ligand VEGFA." (PMID 27822137, 2016). "FUS-CHOP drives tumorigenesis in myxoid liposarcoma by interfering with the expression of transcription factors (including PPARΥ1, PPARΥ2, C/EBPα, C/EBPβ, and C/EBPδ) that regulate the differentiation of adipocyte precursor cells." (PMID 27822137, 2016). "Myxoid liposarcoma is a rare malignancy that is characterized by the expression of the fusion protein FUS-CHOP." (PMID 27822137, 2016). "To examine a potential association between FUS-CHOP and eIF4E expression and the angiogenic activity of myxoid liposarcoma cells, we examined the effect of siRNA knockdown on the expression and activity of proangiogenic factors." (PMID 27822137, 2016). "It has been reported that FUS-CHOP is the main molecular target of trabectedin in myxoid liposarcoma cell line." (PMID 22523595, 2012). "The FUS gene has been shown to be rearranged in a variety of neoplastic conditions, including myxoid liposarcoma, angiomatoid fibrous histiocytoma and acute myeloid leukaemia." (PMID 21406083, 2011). "mir-616 and mir-28 are derived from transposed elements (LINE, L2 family) and are located within two translocation breakpoints, respectively DDIT3, that is often fused to FUS in myxoid liposarcoma, and LPP, that is fused to MLL in a secondary acute leukemia." (PMID 20567512, 2010).
myxoid liposarcoma (continued). "Furthermore, 15 specimens of myxoid liposarcomas were tested either for FUS BrAp or DDIT3 break-apart signals, and seven were found to be positive for these translocations (four cases for FUS BrAp and three for DDIT3 BrAp)." (PMID 40718211, 2025). "Recently, robust evidence has shown that the expression of the FUS-CHOP fusion protein may initiate myxoid liposarcoma in transformed human BMSCs containing five different oncogenic mutations." (PMID 31160689, 2019). "Moreover, transgenic mice that ubiquitously express FUS-CHOP develop myxoid liposarcoma-like tumors at adipose tissue sites." (PMID 27822137, 2016). "Thus, both eIF4E and FUS-CHOP contribute to the angiogenesis observed in myxoid liposarcoma cells through the regulation of angiogenic receptors and ligands." (PMID 27822137, 2016). "Therefore, both eIF4E and FUS-CHOP are critical to myxoid liposarcoma cell proliferation and survival." (PMID 27822137, 2016). "In addition, whereas MLS 402 has a typical type 1 FUS-CHOP transcript found in 24% of patients with myxoid liposarcoma, MLS 1765 has a rare type 8 transcript." (PMID 27822137, 2016). "Together, these data demonstrate that the contribution of FUS-CHOP expression to myxoid liposarcoma cell growth is significant and that targeting the fusion gene and/or its downstream targets such as VEGFR1 and PDGFRα induces significant inhibition of myxoid liposarcoma tumor growth." (PMID 27822137, 2016). "The identification of ∼600 bp of a RAS related leukemia viral oncogene (LOC642550) proximal to the L1 retrotransposon within the NAV3 -SYT1-PAWR gene cluster is also of interest given the known and shared role of rearrangement mediated FUS gene fusions between myxoid liposarcoma and leukemia." (PMID 24505276, 2014). "This suggests that NF-kappaB (p50) transcription in myxoid liposarcoma might be regulated by the FUS/DDIT3 fusion gene." (PMID 20863376, 2010). "In myxoid liposarcomas, a recurrent translocation leads to a fusion of the CHOP gene with FUS or EWS, potentially serving as a LB marker." (PMID 39797974, 2025). "For instance, myxoid liposarcoma is characterized by DDIT3 translocation, most commonly fused with FUS gene, while extraskeletal myxoid chondrosarcoma features a recurrent NR4A3 translocation, most frequently translocated to EWSR1 gene." (PMID 35484289, 2022). "We also characterized the importance of FUS-CHOP, given the widespread presence of this fusion protein in myxoid liposarcoma." (PMID 27822137, 2016). "To identify drugs with antiproliferative activity, we screened 43 drugs for their in vitro antiproliferative activity against two myxoid liposarcoma patient-derived cell lines, MLS 402 and MLS 1765, which have both been confirmed to express FUS-CHOP." (PMID 27822137, 2016). "In myxoid liposarcoma with the FUS-CHOP fusion gene, the pharmacological mechanism of trabectedin is to block the trans-activating chimera, resulting in the detachment of the FUS-CHOP chimera from targeted promoters." (PMID 30487384, 2018). "Displacement of the FUS-CHOP chimera from the promoters of its target genes, blocking its transactivating function, was confirmed in tumor tissues from biopsies of patients with myxoid liposarcomas (MLS) treated with the drug." (PMID 28166781, 2017). "Similar to our finding that FUS-CHOP promotes angiogenesis, we also demonstrated that eIF4E promotes the production of angiogenic factors in myxoid liposarcoma cell lines, as eIF4E siRNA knockdown significantly reduced the expression of VEGFA, VEGFB, and VEGFR3." (PMID 27822137, 2016). "To investigate the importance of FUS-CHOP and eIF4E expression in myxoid liposarcoma, we performed siRNA knockdown of CHOP (using a CHOP-directed siRNA, which also targets FUS-CHOP) or eIF4E in the myxoid liposarcoma cell lines." (PMID 27822137, 2016). "Therefore, our in vivo data may not be representative of myxoid liposarcoma cell lines with more typical FUS-CHOP fusions." (PMID 27822137, 2016).
myxoid liposarcoma (continued). "Fluorescence in situ hybridization (FISH) analysis was done in some of the studies before, which revealed FUS/EWSR1-DDIT3 fusion to be negative and also the absence of MDM2 amplification in this type, which differentiates MPLPS from the conventional myxoid liposarcoma." (PMID 39192930, 2024). "Indeed, this last classification includes also new entities, such as myxoid pleomorphic liposarcoma, a myxoid liposarcoma with non-specific karyotype and lacking the classical gene fusion of DDIT3 with FUS or ESWR1." (PMID 34299136, 2021).
Alzheimer disease (38 papers, 2012 to 2025). A progressive, neurodegenerative disease characterized by loss of function and death of nerve cells in several areas of the brain leading to loss of cognitive function such as memory and language. "For example, TDP-43 and FUS are extensively associated with Alzheimer's disease (AD), Parkinson's disease (PD), and Huntington's disease (HD)." (PMID 38029395, 2024). "The specific amino acid substitutions are at positions 235 and 236 in the arginine/glycine/glycine (RGG)-rich domain of the FUS gene, which resembles the so-called Swedish mutation (K595N/M596L) in APP in Alzheimer’s disease." (PMID 38872230, 2024). "GSK3 hyperactivity has been linked to neurodegeneration before, mainly to Alzheimer’s Disease (AD), and recent studies suggested a possible role of GSK3 in FUS and TDP-43 ALS." (PMID 38363426, 2024). "We quantified VENs and GABRQ‐immunopositive neurons in the anterior cingulate cortex (ACC) in FTD with underlying TDP43 (FTLD‐TDP) (n = 34), tau (FTLD‐tau) (n = 24) or FUS (FTLD‐FUS) (n = 8) pathology, neurologically healthy controls (n = 12) and Alzheimer's disease (AD) (n = 7)." (PMID 35152451, 2022). "While IDR-bearing proteins such as FUS and TDP-43 have been shown to fuse into normal stress granules, mutants of these proteins contribute to irreversible phase transitions of stress granules into pathological stress granules which are hallmarks of age-related diseases such as Alzheimer’s disease." (PMID 32456195, 2020).